CCL5 (C-C motif chemokine ligand 5)
Diseases named in the same sentence as CCL5 in open-access papers (continued):
Sharing a sentence is not in itself a finding about the gene and the disease.
tumor (continued). "Monocytes are actively attracted to the tumor site and differentiate into TAMs as a result of the production of cytokines and chemokines by tumor cells, such as monocyte chemoattractant protein-1 [or chemokine CC ligand (CCL2)], RANTES (or CCL5) and vascular endothelial growth factor." (PMID 25280428, 2014). "As a consequence CCL5 and the CCR5 ligands secreted by tumor cells or by the surrounding T-cells, macrophages, or fibroblasts may support cHL progression by increasing proliferation and by recruiting cells involved in the microenvironment formation." (PMID 24523569, 2014). "CCL5 supports breast malignancy by changing the equilibrium between leukocyte infiltrates in tumors, leading to dominance of cells with tumor-promoting rather than tumor-killing activities." (PMID 24523569, 2014). "Thus, CXCL9, CXCL10, CXCL16, CCL5, and CX3CL1 can be used to efficiently mobilize CTLs from regional lymph nodes to tumor tissues with an objective to enhance CTL-mediated tumor destruction." (PMID 24966464, 2014). "The CD11b+Gr-1int myeloid cells secreted CCL5 and CXCL9 that were important for recruiting NK cells into the tumor microenvironment, demonstrating a role for NLRP3 in the suppression of NK cell activation and promotion of a suppressive tumor environment." (PMID 24273542, 2013). "Several CC chemokine members, including CCL2 (MCP-1), CCL3 (MIP-1α), CCL5 (RANTES), CCL7 (MCP-3), CCL8 (MCP-2), CCL17 (TARC) CCL 20 (MIP-3α), CCL22 (MDC) and CCL23 (MPIF-1), are produced mainly by tumor infiltrating lymphocytes (TIL) and monocytes, and some of them also by cancer cells." (PMID 24213462, 2012). "In such a setting, inflammatory cells that were recruited to the tumor site in response to chemokines such as CCL2 and CCL5 continue releasing the inflammatory cytokines TNFα and IL-1β, whose activities further promote the release of the cancer-related chemokines." (PMID 24213226, 2012). "Furthermore, recent findings obtained in our studies suggest that TNFα and IL-1β exert tumor-promoting activities that are connected to the ability of CCL2 and CCL5 to function as cancer-supporting factors." (PMID 21486440, 2011). "In parallel, we determined the expression of CCL2, CCL5, TNFα and IL-1β in normal breast epithelial duct cells that were in proximity to the tumor cells in biopsies of patients with DCIS, IDC-no-relapse and IDC-with-relapse." (PMID 21486440, 2011). "CCL2, CCL5, TNFα and IL-1β were expressed at very low incidence in normal breast epithelial cells, but their incidence was significantly elevated in tumor cells of the three groups of cancer patients." (PMID 21486440, 2011). "Interestingly, ORMDL3 expression showed a negative correlation with CD8+ T cell activation markers such as PRF1, GZMA, and GZMB, as well as with ISGs such as CCL5 and CXCL10, validating our finding that ORMDL3 serves as a negative regulator of the IFN signaling pathway and anti-tumor immunity." (PMID 40126553, 2025). "CAAs secrete chemokine ligands CCL2 and CCL5, interleukin-1 (IL-1), interleukin-6 (IL-6), tumor necrosis factor-α (TNF-α), and vascular endothelial growth factor (VEGF), and promote cell aggressiveness, tumor progression, migration, and chemotherapy resistance." (PMID 40141437, 2025). "It has been demonstrated that tumor cells release inflammatory cytokines (IL-6, IL-1, TNF-α), chemokines (CCL2, CCL5, CCL15, CCL26), and growth factors (TGFβ), which ultimately recruit BMDCs such as myeloid-derived suppressor cells (MDSCs) and create a favorable niche for tumor development." (PMID 41383620, 2025). "In addition, there are angiogenesis‐related markers, including ANGPT1, CD40LG, HIF1A, CCL5, and GPR87, which could contribute to tumour vascularisation." (PMID 40754672, 2025).
tumor (continued). "Bridging chemotherapy is often used to control tumor progression during this period and has been shown to enhance CAR-T efficacy by reducing immune suppressor cells in the tumor microenvironment and upregulating chemokines such as CCL5, CXCL9, and CXCL10 to improve T cell trafficking." (PMID 40312353, 2025). "The chemokines CCL2 and CCL5 well known attractants of CTLs as well as CXCL9 and CXCL10 powerful chemoattractants of activated CTLs were all highly induced by mIL12 mRNA treatment in both models and likely laid the ground for trafficking and retention of these effectors deep within the tumor cores." (PMID 40321762, 2025). "For instance, tumor-infiltrating CD8+ T cells secreted CCL5,which bound to ACKR1 (atypical chemokine receptor 1)on EC5 cells.ACKR1,a scavenger receptor for inflammatory chemokines, may sequester CCL5 to attenuate T cell recruitment." (PMID 41394809, 2025). "The chemokines CCL2 and CCL5 well known attractants of CTLs as well as CXCL9 and CXCL10 powerful chemoattractant of activated CTLs were all highly induced by mIL12 mRNA treatment in both models and likely laid the ground for trafficking and retention of these effectors deep within the tumor cores." (PMID 40560386, 2025). "Consistently, lacidipine treatment or co‐administration with DOX/cisplatin significantly increased the mRNA expression of CCL5, CD274, CXCL10, and CXCL11 and decreased CCL2 mRNA levels in tumor tissues, thereby promoting immune cell infiltration and converting the “cold” into a “hot” tumor." (PMID 39585774, 2025). "Furthermore, we dissected the contribution of PBRM1 deletion in CRC by regulating inflammatory factors, such as CCL5 and CXCL10 chemotaxis, and activating cytotoxic T cells and killer NK cells, which express NKG2D in the tumor microenvironment through activation of the NF-κB signaling pathway." (PMID 40093909, 2025). "In addition, they also indirectly shift the balance between tumor reactivity and tumor tolerance by recruiting through e.g. CCL3, CCL4, and CCL5 as well as be promoting the induction of T cell-suppressive Tregs through the release of IL-10 or TGF-β, among others." (PMID 40050933, 2025). "In addition, CCL5 positivity in the IC was an independent prognostic marker for RFS in the following subgroups: tumor stage pT3 + 4 (RR = 2.38; p < 0.001) and no chemotherapy (RR = 2.32; p = 0.001)." (PMID 38928033, 2024). "Our finding that MIBC patients with CCL5-positive ICs have a better prognosis (OS, DSS and RFS) suggests that CCL5 expression in ICs, possibly as a surrogate marker for cytotoxic CD8+ T cells and NK cells, may play a role in the anti-tumor immune response." (PMID 38928033, 2024). "However, as CCL5 also recruits MDSCs, TAMs, Tregs, and conventional NK cells via CCR5, CCR5i could prevent a tumor suppressive microenvironment, both directly and indirectly by retaining trNK cells that remove Tregs through FASL." (PMID 39656086, 2024). "This analysis identified a number of potential associations that differed depending on the NK state, including a number of immunostimulatory interactions (Ifng, Ccl5, Il18) involving newly recruited NK cells, but not those that had been retained within the tumor for several days." (PMID 38267402, 2024). "HIF signaling in tumor cells triggers the expression of the CCL-5 (C-C motif ligand 5) chemokine and M-CSF1 (macrophage colony stimulating factor 1) cytokine, attracting macrophages and mesenchymal stem cells to the tumor microenvironment, thereby promoting cell invasion, migration and metastasis." (PMID 38791951, 2024). "Notably, by designing viral particles with anti-EGFR cetuximab and CCL5 chimeric receptors (OV-Cmab-CCL5), Tian and colleagues were additionally able to promote the specific infiltration of various immune cells to EGFR-positive GBM tumours." (PMID 38615034, 2024).
tumor (continued). "CSCs are crucial for monocyte recruitment across tumor types; supernatants from cholangiocarcinoma, hepatocellular carcinoma, or glioblastoma cells under CSC-enriched conditions show elevated levels of tumorigenic macrophage factors like CCL2, CCL5, CSF1, GDF15, IL-13, TGFβ, periostin, and WISP1." (PMID 39068459, 2024). "CCL5 production was lost in vitro in the presence of either recombinant TGFβ or PGE2, and could be enhanced in vivo upon targeting either intratumoral Tregs or tumor cell derived PGE2." (PMID 38267402, 2024). "Furthermore, CCL5, the ligand of CCR5, has shown a tumor-promoting effect in the TME." (PMID 39169402, 2024). "The co-delivery of IRF5 mRNA and CCL5 siRNA allows for the upregulation of IRF5 and downregulation of CCL5, which can help contribute to a significant increase in M1 phenotype macrophages, which can help reduce tumor growth as M1 macrophages can initiate T cell-mediated immune responses." (PMID 37587290, 2024). "By analyzing the effect of MAP2K3 expression levels on chemokines in the tumor immune microenvironment, the results showed elevated expression of several chemokines in the MAP2K3 high expression group; such as CXCL10, CCR5, CCR10, CCL5, CCL7, CCR2, and CCL22 (upper part)." (PMID 38938778, 2024). "When secreted by intratumoral NK cells, XCL1, XCL2, and CCL5 serve as chemoattractants for type 1 conventional DCs (cDC1s), augmenting the recruitment of cDC1s into the TME where these powerful antigen-presenting cells can activate the cytotoxic CD8+ T lymphocytes (CTLs) for tumor attack." (PMID 39114657, 2024). "CCL5 expression was scored as positive vs. negative for TCs and for ICs in the tumor cell area." (PMID 38928033, 2024). "Still in the untreated tumor, when compared to NBTXR3 + XRT + αPD1, NBTXR3 + PRT + αPD1 treatment resulted in a significant increase in the expression of activation markers such as Gzmb, Icos, Prf1 (Perforin 1), as well as chemokine receptor (Ccr7), and chemokine ligand (Ccl5) in cytotoxic T cells." (PMID 39354474, 2024). "Thus, we tested if OSU13 promotes CCL5 and CXCL10 secretion by tumor cells using ELISA." (PMID 38900577, 2024). "Regardless of whether patients received combination therapy or not, the phenomenon of CYP1A1+ tumor cells gathering around CD8+CCL5+ lymphocytes was frequently observed." (PMID 39183447, 2024). "Similarly, CCL5 in colorectal cancer plays a critical role in immune escape through mechanisms of Treg cell recruitment and apoptosis of CD8+ T cells, possibly mediated by direct cytotoxicity of the Tregs against CD8+ T cells, promoting tumor growth." (PMID 38786066, 2024). "has shown that succinate produced by F. nucleatum could inhibit the cGAS-IFNβ pathway, leading to reduced levels of chemokines CCL5 and CXCL10 in the tumor, thereby limiting the migration of CD8+ T cells to TME and suppressing the anti-tumor response of CD8+ T cells." (PMID 38023192, 2023). "An ELISA assay revealed that HRSdx cells secreted higher amounts of molecules involved in the immunosuppressive monocyte tumor education (IL-13, TGF-β, M-CSF, L-lactate, and PGE2), stromal cell proliferation (FGF), T-cell, fibroblast, and monocyte recruitment, and prognostic markers (CCL5 and TARC)." (PMID 38067159, 2023). "We examined whether NF-κB regulated the transcription of CCL5 or not in tumor cells with Arf1 inhibitor treatment or Arf1 knockdown, and found that inhibiting Arf1 significantly upregulated the phosphorylation level of p65 protein (p-p65) in CT26 cells." (PMID 39872623, 2023). "Additionally, our data suggest that the CCL5/CCR5 axis might play a role in tumor-infiltration of CD8+ TRM cells, in line with a strong correlation between the expression of CCL5 and CD8+ T cell infiltration across different types of cancer." (PMID 37448786, 2023).
tumor (continued). "In addition, the elevated exosome miRNA-155 during the co-culture of tumor cells and adipocytes can promote the production and release of adipocytes CCL2 and CCL5 by targeting the SOCS6/STAT3 pathway, thereby regulating the function and polarity of macrophages and promoting tumor progression." (PMID 37666813, 2023). "The main mediators of tumor‐induced polarization of macrophages from M1 to M2 types are chemokines and cytokines, such as prostaglandin E (PGE) 2, milk fat globule‐E8 (MFG‐E8), granulocyte/macrophage colony‐stimulating factor (GM‐CSF), CSF‐1, CCL5, IL‐4, IL‐6, and TGF‐β." (PMID 37937304, 2023). "Tumor-specific IL-7Rhi CD8+ T cells (cluster 4) expressed intrinsic cytotoxic mediators including natural killer cell granule protein 7 (Nkg7), killer cell lectin receptor D1 (Klrd1), cathepsin W (Ctsw), cystatin F (Cst7), and Ccl5, suggesting a capacity for cytotoxicity." (PMID 37459511, 2023). "Furthermore, FLOT1 depletion-boosted DNA damage activated STING signaling pathway and promoted the production of CCL5 and CXCL10 that can drive CD8+ T lymphocytes chemotaxis, thereby reprogramming tumor immune microenvironment and triggering the antitumor immune response." (PMID 37131290, 2023). "Prior studies have noted the ability of CAAs in secreting high abundance of IL-6, IL-1β, CCL2, chemokine (C–C motif) ligand 5 (CCL5), tumor necrosis factor-α (TNF-α), vascular endothelial growth factor (VEGF) and leptin, which could enhance tumor invasion and immune escape." (PMID 37127625, 2023). "Lastly, it is possible that KLF13 impacts tumoral CCL5 expression, with the latter molecule having major effects on immune cell infiltration into multiple tumor types, and with predicted positive as well as negative effects on tumor immune response." (PMID 38067370, 2023). "Some studies suggest that RANTES/CCL5 production may lead to a more immune-suppressive activity in tumor microenvironment (TME), while other evidence suggests that RANTES/CCL5 is in favor of tumor immunity." (PMID 36983384, 2023). "Moreover, CCL5 and XCL1 produced by tumor-infiltrating NK cells and innate lymphoid cells promoted the recruitment and activation of XCR1+ cDC1s, fostering NK-cDC1 axis-related control of tumor growth." (PMID 36949244, 2023). "In addition, CCL5 also enhances antitumor immunity by recruiting antitumor T cells and dendritic cells to the TME and therefore promotes the immunotherapy response in different tumor types." (PMID 37040518, 2023). "Moreover, we found that the C4 subpopulation highly expressed cystatin B (CSTB), matrix metalloproteinase 9 (MMP9), chemokine C-C ligand 5 (CCL5), and macrophage migration inhibitory factor (MIF), which have the characteristics of promoting tumor cell migration and invasion." (PMID 37715019, 2023). "Furthermore, RocA dramatically activated the cGAS (cyclic GMP-AMP synthase)-STING (stimulator of interferon genes) signaling pathway, and the inhibition/depletion of STING ablated the up-regulation of CCL5 and CXCL10, NK cell infiltration, and tumor regression induced by RocA." (PMID 35002511, 2022). "The distribution of T cells in the tumour environment could be guided by the presence of chemoattractants (such as CCL5) in the stroma, rather than the tumour cell regions." (PMID 35260891, 2022). "However, only STINGR284S mRNA, not STINGWT mRNA, stimulated the production of anti-tumor cytokines, such as CCL5, CXCL10, IL29, IL6, IFNβ and TNFα." (PMID 36498833, 2022). "Because the primary tumors after treatment were entirely ablated, tumor samples could not be collected, so we only focused on studying the systemic effects of CCL5 after treatment in the spleen and blood." (PMID 35327361, 2022). "In this study, we mainly studied the role of host-derived CCL5 in the immune response after cryo–thermal therapy, and we are carrying out another study on combinations of cryo–thermal therapy and the antibody inhibition of CCL5/RANTES or CCR5 blockade in the 4T1 tumor model." (PMID 35327361, 2022).
tumor (continued). "Therefore, we speculate that in addition to the secretion of CCL5 by tumor cells, there is a mechanism similar to PD1/PDL1: CCL5 expressed by T cells combines with the CCR5 receptor on the surface of tumor cells to form the CCL5/CCR5 complex." (PMID 36033472, 2022). "CCR5-CCL4/CCL5 and CXCR3-CXCL9/CXCL10/CXCL11/CXCL13 axis were significantly correlated with CD 4 T and CD 8 T cells, indicating that these chemokine–receptor pairs may recruit the T lymphocytes into tumor." (PMID 35530341, 2022). "COX-2/PGE2 can also inhibit the secretion of CCL5 and XCL1 by natural killer (NK) cells and the expression of CCR5 and XCR1 in conventional type 1 dendritic cells (cDC1), which can impair the function of NK cells and the accumulation of cDC1 in the TME, which are responsible for tumor immunity." (PMID 35603146, 2022). "In addition, CCL5 can mediate the recruitment and chemotaxis of Tregs, macrophages, DCs and MDSCs, as well as induce the Th2 polarization of CD4+ T cells, which consequently promote tumor growth and metastasis." (PMID 35327361, 2022). "First, CCL5 produced by cancer cells attracted T cells into the tumor tissue, then T cells activated cancer antigens, then tumor antigens induced CXCL9 to secrete by immune cells dependent on the release of IFN-γ, and finally CXCL9 promotes further tumor infiltration by T cells." (PMID 36618371, 2022). "Moreover, a drop in CD8 T cells but not in CD4 T cells is observed when CCL5-treated tumor cells are co-cultured with peripheral blood mononuclear cells (PBMCs)." (PMID 36429101, 2022). "The CCL5/ C-C motif chemokine receptor 5 (CCR5) axis gains increasing attention due to its involvement in tumor progression through multiple mechanisms, including immunosuppressive polarization, metabolic reprogramming, and ECM remodeling, facilitating migration and invasion of tumor cells." (PMID 35216235, 2022). "Moreover, CCL5 can induce the immunosuppressive polarization of macrophages, initiate the Th2 differentiation of CD4+ T cells and recruit Tregs to form tumor suppressive environments." (PMID 35327361, 2022). "In addition to reduced tumor growth, EVT801 decreased tumor hypoxia, favored sustained tumor blood vessel homogenization (i.e., leaving fewer and overall larger vessels), and reduced important immunosuppressive cytokines (CCL4, CCL5) and myeloid-derived suppressor cells (MDSC) in circulation." (PMID 36970050, 2022). "CCL5, another cytokine produced by adipocytes, has also been shown to enhance TAM recruitment into residual tumors in a conditional model of ErbB2 overexpression in mice, leading to increased collagen deposition within the tumor site and eventual recurrence of the tumor." (PMID 35435599, 2022). "In particular, CCL5 has been shown to support the αvβ3 integrin-mediated tumor cell migration through activation of the PI3K/AKT and NF-kB signaling pathways, and by increasing the production of matrix metallopeptidases 2 (MMP-2) and MMP-9, able to promote tumor cell invasiveness." (PMID 36428727, 2022). "Meanwhile, the expression level of CCL5 at the tumor site determined the effectiveness of the antitumor response, which may be related to the increased number of NK cells and CD8+ T cells at the tumor site." (PMID 35710862, 2022). "CCL5−/−-induced M1 macrophage polarization played a crucial role in the inhibition of Tregs and Th2 cell differentiation and the cytotoxic of CD8+ T cells, which would be exclusively responsible for mediating cryo–thermal-triggered, long-lasting anti-tumor memory immunity." (PMID 35327361, 2022). "Moreover, we observed that the production of CCL4, CCL5, CXCL9 and CXCL10 chemokines was induced by the co-culture of murlentamab-opsonized SKOV3-R2+ tumor cells with both M0 and TAM-like MDMs, while the normal fucosylated form 3C23K-CHO did not demonstrate any effects." (PMID 33924378, 2021).